RNU2-19P (RNA, U2 small nuclear 19, pseudogene)
Gene: Small nuclear RNA gene on chromosome 1 (205,566,716 to 205,566,799, forward strand). Ensembl gene ENSG00000253097.
Homologues: Orthologues: rabbit U2 (65% identical). Paralogues in human: RNU2-23P (77% identical), RNU2-18P (70% identical), RNU2-28P (70% identical), RNU2-2 (69% identical), RNU2-6P (69% identical), U2 (69% identical), RNU2-41P (68% identical), RNU2-58P (68% identical), U2 (68% identical), RNU2-17P (67% identical), RNU2-24P (67% identical), RNU2-36P (67% identical), and 65 more.